IRS1 (insulin receptor substrate 1)
Diseases named in the same sentence as IRS1 in open-access papers (continued):
Sharing a sentence is not in itself a finding about the gene and the disease.
colon cancer (31 papers, 2009 to 2025). "In a xenograft tumor model, abrogation of TGFβ signaling led to increased colon cancer cell proliferation, decreased apoptosis and enhanced tumor growth in vivo, associated with elevated expression and activation of IRS-1." (PMID 28414818, 2017). "Since loss of TGFβ signaling is frequent in colon cancer, our study points to IRS-1 as a potential therapeutic target for colon cancer management." (PMID 28414818, 2017). "Recently, we demonstrated that IGF-1R kinase inhibitor PQIP causes marked antitumor activity in these colon cancer cell lines by abrogating the IGF-1R mediated activation of IRS1/Akt to inhibit survival signaling, and inducing apoptosis." (PMID 24173770, 2014). "The frequent loss of TGFβ signaling in colon cancer may account for increased IRS-1 expression." (PMID 28414818, 2017). "The expression level of IRS1 was found to be higher in colon cancer cells in comparison with the normal cell." (PMID 32812032, 2020). "Loss or attenuation of TGFβ activation leads to elevated expression and phosphorylation of IRS-1 in colon cancer cells, resulting in enhanced cell proliferation, decreased apoptosis and increased tumor growth in vitro and in vivo." (PMID 28414818, 2017). "For instance, miRNA-145 targets the insulin receptor substrate-1 and thus inhibits the growth of colon cancer cells." (PMID 28177900, 2017). "In our study, we show, for the first time, that TGFβ signaling inhibits IRS-1 expression and activation in colon cancer cells in vitro and in vivo and that upregulated IRS-1 contributes to attenuation of TGFβ signaling-mediated tumor suppressive phenotypes." (PMID 28414818, 2017). "Taken together, our study suggests a novel model of crosstalk between TGFβ/Smad3 signaling and IRS-1 in colon cancer cells." (PMID 28414818, 2017). "It has been shown that IGF-1R signaling is important for proliferation of colon cancer cells and that IRS-1 is one of the main adaptor proteins required for IGF-1R signaling." (PMID 28414818, 2017). "Taken together, our studies demonstrate that TGFβ/Smad3 inhibits cell proliferation and induces apoptosis through down-regulation of IRS-1 expression/activation in colon cancer cells." (PMID 28414818, 2017). "In this study, we show that abrogation of TGFβ signaling increased expression and phosphorylation of IRS-1 in colon cancer cells in vitro and in a tumor xenograft model in vivo." (PMID 28414818, 2017). "To determine the mechanisms underlying the suppressive effect of TGFβ signaling on growth of colon cancer cells in the xenograft studies, we determined the expression and phosphorylation of IRS-1 in xenograft tumors by immunohistochemistry (IHC) staining." (PMID 28414818, 2017). "The results show that IRS-1 expression and phosphorylation are decreased in CBS-RII cells compared with control cells, indicating that enhancing TGFβ signaling by TGFβ RII upregulation suppresses the expression and activation of IRS-1 in colon cancer cells." (PMID 28414818, 2017). "Further studies showed that TGFβ signaling suppresses expression and phosphorylation of IRS-1 in colon cancer cells." (PMID 28414818, 2017). "In this study, we have uncovered a novel crosstalk between TGF-β and IGF-1R signaling pathways through the adaptor protein, IRS-1, in colon cancer cells." (PMID 28414818, 2017). "miR-145 has also been proposed as a tumor suppressor that can target the 3′-untranslated region of the insulin receptor substrate-1 gene and dramatically inhibit the growth of colon cancer cells." (PMID 25861353, 2015). "On the contrary, miR-126 has also been reported to be a tumor suppressive miRNA, inhibiting tumor cell growth through targeting p85beta in colon cancer cell lines, and targeting IRS-1 in HEK293 and MCF-7 cells, respectively." (PMID 21304604, 2011). "Although it has been reported that miR-145 targets IRS-1 in colon cancer cells, we excluded miR-145 in this study because of its low expression level." (PMID 21464990, 2011).
colon cancer (continued). "Up regulation of IRS1 were found in colon cancer, while downregulation of IRS1 levels were found in differentiating cells." (PMID 20977730, 2010). "miR-145 has been proposed as a tumor suppressor and it had been shown previously that miR-145 targets the 3' UTR of IRS-1 and dramatically inhibits the growth of colon cancer cells." (PMID 19912656, 2009). "Furthermore, we present novel data on the positive prognostic value of stromal RUNX3, SMAD4, and IRS-1 in colon cancer." (PMID 36900240, 2023). "Therefore, our study uncovers another mechanism by which IRS-1 expression is regulated in colon cancer." (PMID 28414818, 2017). "Further studies are needed to investigate whether TGFβ/Smad3 regulates Cbl-b expression and/or activity in colon cancer cells and whether Cbl-b is responsible for suppression of IRS-1 expression by TGFβ/Smad3 signaling." (PMID 28414818, 2017). "Given that loss of TGFβ signaling occurs frequently in colon cancer, an important implication of our study is that IRS-1 could be a potential therapeutic target for colon cancer treatment." (PMID 28414818, 2017). "Given their function in regulating cell cycle and survival, effects on cyclin D1 and XIAP may contribute to IRS-1 mediated enhancement of cell proliferation and inhibition of apoptosis in colon cancer cells." (PMID 28414818, 2017). "Furthermore, miR-126 regulates cell proliferation, migration and invasion of colon cancer cells by targeting IRS-1." (PMID 28414818, 2017). "Taken together, these results indicated that abrogation of TGFβ signaling led to increased expression and activation of IRS-1 in colon cancer cells in vivo, suggesting that TGFβ may regulate IRS-1 expression and activation." (PMID 28414818, 2017). "Since Smad3 is an important effector in TGFβ signaling, we next determined whether downregulation of Smad3 would affect IRS-1 expression and activation in colon cancer cells." (PMID 28414818, 2017). "However, while an IRS-1 resistant to miR-145 can rescue colon cancer cells from miR-145-induced growth inhibition, an IGF1R resistant to miR-145 failed to rescue colon cancer cells from growth inhibition." (PMID 25474488, 2014). "miR-145 has been shown to regulate IRS-1 in colon cancer and IRS-1/2 in HCC." (PMID 25628647, 2014). "Given that the TGFβ signaling pathway is lost in approximately 30% of colon cancer patients and that IRS-1 has been implicated in the progression of various cancers including colon cancer, our study suggests that IRS-1 could be a potential therapeutic target in colon cancer management." (PMID 28414818, 2017). "In addition, miR-128 suppresses cell growth and metastasis by targeting IRS-1 in colon cancer." (PMID 28414818, 2017). "High expression levels of IRS1, RUNX3, and SMAD4 are positive prognostic factors in stage I–III colon cancer." (PMID 36900240, 2023). "In this study, we apply deep learning to digitized pathology images to explore compartment level expression and prognostic impact of IRS-1, IRS-2, RUNX3, and SMAD4 in resected tumors from 452 colon cancer patients." (PMID 36900240, 2023). "In this study, we explore the expression and prognostic impact of IRS-1, IRS-2, RUNx3, and SMAD4 in colon cancer." (PMID 36900240, 2023). "We present the first study that differentiates between expression of IRS-1 and 2, RUNX3 and SMAD4 in the tumor epithelial and stromal compartments of colon cancer patients." (PMID 36900240, 2023). "Therefore, IRS-1 could be a potential therapeutic target for colon cancer treatment." (PMID 28414818, 2017). "Previous studies have shown that overexpression of PES1 can lead to an increase in the percentage of 32D IRS-1 cell in the G2/M phase, whereas knockdown of PES1 can shorten the G2/M phase for colon cancer cells as well as repressing the growth of xenografts." (PMID 27409667, 2016).
colon cancer (continued). "Pathway inhibition in human colon tumour (HCT116) cells was explored by reverse phase protein array (RPPA) analysis, which showed a dose‐dependent response in IRS‐1 expression." (PMID 27304907, 2016). "IRS1, an insulin signaling pathway gene, expressed stronger immunostaining in colon adenomas from FAP and in colorectal cancers and is suggested to play a role in colon tumor development." (PMID 38609520, 2024). "Based on weak to moderate correlations with tumor epithelial and stromal RUNX3, IRS-1, CD8+ TIL density, and stromal miR126, stromal SMAD4 expression in colon cancer is likely involved in complex interactions between tumor epithelial cells and different types of stromal cells." (PMID 36900240, 2023). "Two colon cancer cell lines (HCT116 and LoVo) were used to verify whether the expression of insulin receptor substrate 1 (IRS‐1) could impact the half maximal inhibitory concentration (IC50) of oxaliplatin after chronic insulin treatment." (PMID 32248666, 2020). "Here we show that IRS-1 regulates expression of cyclin D1 and XIAP in colon cancer cells." (PMID 28414818, 2017). "Interestingly, it was previously shown that miR-145 can target insulin receptor substrate-1 (IRS-1) and IGF1R in colon cancer cells." (PMID 25474488, 2014). "We found that IGFBP-rP1 could upreguate TAGLN, downregulate SOX9, IRS1, P15, AREG, IER5L, KRT8 in these colon cancer cells, indicating that these genes may be the important IGFBP-rP1 responsible genes in colon cancer." (PMID 20977730, 2010). "In addition to c-Myc, miR-145 has also been suggested to target the human insulin receptor substrate-1 (IRS-1) and type I insulin-like growth factor receptor (IGF-IR) in colon cancer." (PMID 20098684, 2010). "Downregulation of IRS1 and SOX9 by both IGFBP-rP1 and sodium butyrate in colon cancer cells indicated that these two genes may play important roles in the differentiation and apoptosis induction process in colon epithelium." (PMID 20977730, 2010). "The upreguation of TAGLN and downregulation of SOX9, IRS1, P15, AREG, IER5L, KRT8 in RKO, SW620 and CW2 colon cancer cells indicated these genes may be the target molecules for the biological behaviour of IGFBP-rP1 in colon cancer." (PMID 20977730, 2010). "Our studies identify a novel crosstalk between TGFβ and IGF-1R signaling through the adaptor protein, IRS-1, indicating that one of the mechanisms by which TGFβ elicits its tumor suppressor function is through inhibition of IRS-1 expression and activation in colon cancer cells." (PMID 28414818, 2017). "It was shown that an IRS-1 lacking its 3' UTR is no longer downregulated by miR-145 and rescues colon cancer cells from growth inhibition induced by miR-145." (PMID 19912656, 2009).
Alzheimer disease (28 papers, 2015 to 2026). A progressive, neurodegenerative disease characterized by loss of function and death of nerve cells in several areas of the brain leading to loss of cognitive function such as memory and language. "It has been shown that dysregulation of the expression of GLP-1 and GIP receptors and impairment of insulin receptor substrate 1 (IRS-1) are implicated in the development and progression of neurodegenerative diseases such as Alzheimer’s disease (AD)." (PMID 40498212, 2025). "Conversely, overexpression of HIF-1α in the brains of individuals with Alzheimer’s disease (AD) has been shown to inhibit the activation of insulin receptor substrate 1 in the neurons." (PMID 38731800, 2024). "This is based on previous reports that pSer312 and pSer616 insulin receptor substrate-1 (IRS-1) is upregulated in the neurons in Alzheimer’s disease and mild cognitive impairment (MCI) cases." (PMID 39698505, 2021). "In the brain, phosphorylation of IRS1 at specific Ser sites increases in patients with Alzheimer’s disease (AD) and its animal models." (PMID 31426549, 2019). "Previous studies on patients with Alzheimer’s disease suggested that dysfunction in IRS-1 may play a role in cognitive decline." (PMID 40284205, 2025). "Focusing on the top three studies, the most cited article (“Defects in IGF-1 receptor, insulin receptor and IRS-1/2 in Alzheimer’s disease indicate possible resistance to IGF-1 and insulin signalling”) was published in the Neurobiology of Aging in 2010 and was cited 602 times." (PMID 41017976, 2025). "In detail, pSer312-IRS-1 levels were associated with greater brain atrophy rather than p-panTyr-IRS-1 levels, as a result of their deteriorating and protective role in Alzheimer’s disease, respectively." (PMID 34943180, 2021). "In the central nervous system, studies on postmortem brain tissues of patients with Alzheimer’s disease (AD) have revealed increased phosphorylation of IRS1 at hSer312/mSer307, hSer616/mSer612, hSer636/mSer632, and hSer639/mSer635 compared with that in non-AD control subjects." (PMID 31426549, 2019). "In a streptozotocin-induced astrocytotoxicity model for Alzheimer’s disease, memantine ameliorated BDNF and GDNF decline in astrocytes along with phosphorylation of IRS-1, Akt, and GSK-3α/β." (PMID 32782018, 2020). "Signaling molecules downstream of the IR, including IR substrate (IRS)-1/2, PI3 kinase (PI3K) and phospho-Akt, are significantly down-regulated in the frontal cortex and hippocampus of Alzheimer’s disease patients and in Alzheimer’s disease mouse models." (PMID 27639375, 2016). "However, by contrast, both IRS-1 and IRS-2 expressions decrease in neurons of humans with Alzheimer’s disease and both insulin and IGF-1 signaling are patently disturbed in brains affected by Alzheimer’s disease." (PMID 25755673, 2015).
Hepatic steatosis (26 papers, 2009 to 2025). Steatosis is a term used to denote lipid accumulation within hepatocytes. "We therefore suggest that the suppressed expression of IRS-1 had caused downstream inhibition of lipogenic enzymes, ultimately reducing hepatic steatosis in our in vitro model." (PMID 38630788, 2024). "Collectively, our findings suggest that ANXA1 reduces the development of hepatic steatosis and the associated liver injury by inhibition of RhoA activity and restoration of IRS-1 signaling." (PMID 30972066, 2019). "FOXF2 has been shown to downregulate the expression of Insulin Receptor Substrate 1 (IRS1) in adipose tissue, thereby reducing glucose uptake, and HDAC9 has been implicated in adipocyte hypertrophy, IR, and hepatic steatosis." (PMID 40699860, 2025). "Conversely, inhibition of IRS1 with NT157 almost completely negated the protective effects of JWQZG against hepatic steatosis." (PMID 40221773, 2025). "Improved insulin signaling through the regulation of IRS-1 was also identified as a mechanism of action whereby Afriplex GRTTM ameliorated hepatic steatosis." (PMID 38630788, 2024). "This deteriorated adipose tissue function contributes to impaired hepatic insulin sensitivity (as demonstrated by decreased IRS1 expression) and pronounced hepatic steatosis (as evident by abundant lipid droplets and higher liver weight)." (PMID 37520561, 2023). "This study showed a significant correlation between MZ supplementation and decreased the risk of fatty liver and CMS and has implication in the management of fatty liver and insulin resistance by regulating PPAR-γ, IRS-1, NF-κB and Nrf2 pathways." (PMID 28804442, 2017). "This will further decrease the circulating insulin levels, which would result in reduced lipid synthesis and storage via Irs1 signalling, leading to the improvement of the hepatic steatosis." (PMID 27708333, 2016). "Our in vivo models of hepatic steatosis with perturbed insulin concentrations had relatively increased IRS-1 expression at high insulin concentrations (T2FLD), and relatively increased IRS-2 at low insulin concentrations (T1FLD)." (PMID 22745692, 2012). "Unfortunately, we were not able to find the underlying mechanism that connects hepatic steatosis with defective insulin signaling beyond the IRS1/PI3K reduction." (PMID 29028831, 2017). "Thus, in vivo hypoinsulinemic T1FLD mice developed hepatic steatosis, which was associated with an up-regulation of IRS-2 relative to IRS-1, and an increase in FATP-2 and FATP-5 mRNA expression, as well as greater FATP-2 protein levels." (PMID 22745692, 2012). "In addition, HCV core protein can cause the downregulation of insulin receptor substrate-1 (IRS-1) signaling, the elevation of inflammatory cytokine, and hepatic steatosis due to impaired secretion of very low lipoprotein cholesterol or decreased fatty acid beta-oxidation." (PMID 26913058, 2016). "Afriplex GRTTM reduced hepatic steatosis in oleic acid induced C3A liver cells by modulating SREBF1, ChREBP and IRS-1 gene expression." (PMID 38630788, 2024). "Dietary leucine supplements in drinking water were found to improve glucose tolerance and insulin sensitivity by decreasing tyrosine phosphorylation of insulin receptor substrate-1 (IRS-1) and decreasing insulin-stimulated serine phosphorylation of AKT then reducing hepatic steatosis." (PMID 37432261, 2023).